RNU1-104P (RNA, U1 small nuclear 104, pseudogene)
Gene: Small nuclear RNA gene on chromosome 12 (127,321,355 to 127,321,529, forward strand). Ensembl gene ENSG00000253089.
Homologues: Orthologues: chimpanzee U1 (99% identical), zebrafish U1 (39% identical), mouse Gm23240 (38% identical), zebrafish U1 (38% identical), zebrafish U1 (37% identical), dog U1 (31% identical). Paralogues in human: RNVU1-7 (52% identical), RNU1-1 (51% identical), RNU1-2 (51% identical), RNU1-27P (51% identical), RNU1-28P (51% identical), RNU1-3 (51% identical), RNU1-4 (51% identical), RNVU1-18 (51% identical), RNVU1-29 (51% identical), RNVU1-31 (51% identical), U1 (51% identical), RNVU1-28 (51% identical), and 134 more.